APC (APC regulator of Wnt signaling pathway)
Diseases named in the same sentence as APC in open-access papers (continued):
Sharing a sentence is not in itself a finding about the gene and the disease.
breast cancer (continued). "While APC had been linked to lung cancer in previous studies, the relation with breast cancer has not yet been established." (PMID 37195695, 2023). "The overall APC gene variation rate in breast cancer patients ranges between 0.4 and 18%." (PMID 37277882, 2023). "In addition, the methylation status of RARβ2 and APC genes in serum samples was superior to traditional tumor markers in the detection of breast cancer." (PMID 36765815, 2023). "Both genetic and epigenetic alterations in APC have also been identified in human breast cancer." (PMID 37655825, 2023). "Until further investigation can be completed into the specific impact of frequent and rare APC and BRCA2 variants in Arab cohorts, all patients carrying either APC or BRCA2 variants should be considered at elevated risk of CRC and breast cancer and be offered screening accordingly." (PMID 37306523, 2023). "It is well-established that APC is abnormally methylated in both breast cancer and ovarian cancer, therefore it cannot be ruled out that APC might affect cancer cell responsiveness to anti-tumor drugs through gene silencing induced by promoter methylation." (PMID 33968756, 2021). "APC germline mutations were detected in two patients with breast cancer and no family history or other malignancy resembling our results." (PMID 35127508, 2021). "Our observation, which may conflict with the role of APC in colorectal and breast cancers, is supported by previous DNA methylation studies of BLCA for clinical prognosis." (PMID 34540821, 2021). "Survival analysis of METTL14, ZC3H13 and APC in breast cancer patients (the PrognoScan)." (PMID 33363011, 2020). "Thus, a decrease in APC protein level leads to abnormal activation of Wnt signaling pathway in breast cancer." (PMID 33363011, 2020). "Furthermore, it was found that APC was necessary to induce BER in metastatic breast cancer stem cells (mBCSCs) following treatment with the PARP inhibitor ABT-888 in mBCSCs pre-treated with the small molecule Quinacrine." (PMID 33105836, 2020). "In addition, it was previously shown that the loss of APC resulted in a decrease in overall survival in non-small cell lung cancer (NSCLC) and breast cancer." (PMID 33105836, 2020). "Using primary mammary tumor cells isolated from a MMTV-PyMT transgenic mouse crossed with an ApcMin/+ mouse, we made the novel observation that the loss of APC in MMTV-PyMT;ApcMin/+ mouse mammary cells decreased doxorubicin-induced DNA double-stranded breaks compared to wild-type specimens." (PMID 33105836, 2020). "Specifically, Wnt signaling activation in metaplastic breast cancers is caused mainly by genetic changes, such as CTNNB1 and APC mutations, whereas Wnt signaling activation in BLBCs and TNBCs is associated mainly with the strong expression of nuclear β-Catenin." (PMID 33234169, 2020). "However, since the expressions of METTL14 and ZC3H13 in breast cancer were significantly reduced, this process is reversed, resulting in a decrease in the stability of APC mRNA and inhibiting the protein level of APC." (PMID 33363011, 2020). "Although Wnt signaling was first described as inducing breast tumors in mice and Wnt/β-catenin signaling is activated in a proportion of multiple subtypes of human breast cancers, the typical mutations in components of the pathway found in CRC (APC, CTNNB1, AXIN2) are rare in breast carcinomas." (PMID 33227961, 2020). "Methylation of APC, FOXA1, and RASSF1A in cell free DNA served as a best performing cassette in terms of diagnostic and prognostic value, revealing a sensitivity, specificity and accuracy over 70% suggesting its putative utility in management of breast cancer." (PMID 31608277, 2019).
breast cancer (continued). "For example, women without breast cancer, but at high risk (Gail model score) are more likely to have aberrant methylation of the tumor suppressor genes APC and RASSF1 compared with women at low risk." (PMID 28693600, 2017). "Next, we asked whether concurrent loss of APC and APC2 was breast cancer subtype specific and detected an enrichment of dual loss for triple-negative breast cancers (Fisher’s exact test two tailed P<0.0001 in both data sets)." (PMID 27694902, 2017). "Hence, we conducted a meta-analysis to quantitatively assess the clinicopathological significance and diagnosis role of APC methylation in breast cancer." (PMID 27191268, 2016). "In conclusion, this was the first meta-analysis about APC promoter methylation and breast cancer." (PMID 27191268, 2016). "Subgroup analysis for the relationship between APC promoter methylation and breast cancer." (PMID 27478702, 2016). "Additionally, we comprehensively evaluated the diagnostic value of APC methylation for breast tumors, in order to provide evidence for the future application of APC in the prevention, diagnosis and treatment of breast cancer." (PMID 27191268, 2016). "Taken together, these results indicated that miR-142 was a potential suppressor of Wnt/β-catenin signaling, which is inconsistent with a recently study reported that miR-142-3p activated the canonical WNT signaling pathway in human breast cancer stem cells through suppression of APC." (PMID 27348426, 2016). "Adenomatous polyposis coli (APC) is an important tumor suppressor gene in breast cancer." (PMID 27191268, 2016). "Methylation in APC gene has been investigated in several types of malignancies, including colorectal cancer, prostate cancer, hepatocellular carcinoma, and breast cancer." (PMID 27191268, 2016). "We also demonstrated that cisplatin in combination with PP2 or SP600125 could be clinically beneficial, as inhibition of Src or JNK in an APC-mutant breast cancer patient may alleviate the resistance induced by mutant APC." (PMID 26049416, 2015). "Elevated basal, ligand-independent, Wnt signaling in some canine breast cancer cells is not caused by classical mutations in APC, β-Catenin or GSK3β but, at least partially, by enhanced LEF1 expression." (PMID 26205886, 2015). "However, previous studies have demonstrated that APC mediates sensitivity to cisplatin in multiple tumor types including breast cancer." (PMID 26049416, 2015). "It has been demonstrated that only 6% of breast cancers harbor mutations in the APC gene, and no mutations in CTNNB1 have been identified in breast cancer." (PMID 26124080, 2015). "Despite this mechanistic information, the role of APC in mediating breast cancer chemotherapeutic resistance is currently unknown." (PMID 26049416, 2015). "Mutations of genes encoding intracellular components of the canonical pathway, including APC (encoding adenomatous polyposis coli), CTNNB1 (encoding β-catenin) and AXIN, are frequent in colorectal and hepatocellular cancers, but are rare in breast cancer." (PMID 25848952, 2015). "Regarding other tumor sites, papillary thyroid carcinoma appeared in one family of APC group 3; liver and breast cancers were reported in two families each: one from group 2 and one from group 3; uterine cancer was reported in one group 1 and one group 4 (MAP) family." (PMID 23561487, 2013). "Comparison of methylation profiles of the 12 breast cancer candidate genes in the paired lymph node metastasis to the matched normal tissue showed significantly higher methylation levels for APC, BMP6, BRCA1 and P16 genes (P < 0.05 and P < 0.01, P < 0.0001, P < 0.05; respectively)." (PMID 22695536, 2012). "The aim of this study was to determine whether inhibition of tankyrases in breast cancer cells, the majority of which have normal β-catenin and APC, also results in stabilization of Axin and attenuation of Wnt signalling and cell growth." (PMID 23144924, 2012).
breast cancer (continued). "Here, we examined the effect of inhibiting tankyrases in breast cancer cells with normal APC." (PMID 23144924, 2012). "A quantitative methylation-specific PCR assay was used to analyze the DNA methylation status of 6 genes (DAPK, TWIST, HIN-1, RASSF1A, RARβ2 and APC) in 9 normal breast tissue samples from unaffected women and in 56 paired cancerous and normal tissue samples from breast cancer patients." (PMID 20226036, 2010). "A total of 6 genes (DAPK, TWIST, HIN-1, RASSF1A, RARβ2 and APC) was analyzed for promoter methylation in normal breast tissues from 9 reduction mammoplasty specimens and in matched normal and cancerous tissues from 56 breast cancer patients using qMSP." (PMID 20226036, 2010). "Besides secreted inhibitors, two studies also reported frequent methylation of the APC gene in breast carcinomas." (PMID 19570204, 2009). "It remains to be determined to what extent epigenetic alterations of the APC gene might characterise specific breast cancer phenotypes." (PMID 18841156, 2008). "Moreover, hypermethylation of APC can be detected in breast aspirate fluid DNA and serum DNA from patients with pre-invasive and early-stage breast cancer." (PMID 18841156, 2008). "Similar to findings in colorectal cancers, it has been suggested that disruption of the APC/β-catenin pathway may be involved in breast cancer." (PMID 18841156, 2008). "Epigenetic inactivation due to hypermethylation is well established for APC in breast carcinoma but as yet, few studies have addressed whether epigenetic alterations of the APC gene might characterise specific breast cancer phenotypes." (PMID 18841156, 2008). "APC promoter methylation was detectable in 53 of 54 (98%) of breast carcinoma samples." (PMID 18841156, 2008). "Finally, we show here for the first time the possible involvement of the APC/C in the regulation of Skp2 abundance in breast cancer cells." (PMID 16859513, 2006). "Hypermethylation of the APC promoter CpG island was detected in 18 of 50 (36%) primary breast cancers and in none of 21 non-cancerous breast tissue samples, although no mutations of the APC and β- catenin were found." (PMID 11437404, 2001). "In addition, it was shown that patients with APC-deficient breast cancer lacked estrogen and progesterone receptors and demonstrated decreased overall survival as compared with patients with APC-positive breast cancer." (PMID 37108784, 2023). "In mouse mammary tumor cells, the pharmacological inhibition or genetic silencing of MDR1 or MRP1, respectively, decreased the TIC population and increased DOX-induced apoptosis, supporting the use of ABC transporter inhibitors as therapeutic targets in APC-deficient tumors." (PMID 37108784, 2023). "Woodage and colleagues reported a higher overall cancer risk, excluding non-melanoma skin cancer in AJ carrying the APC I1307K variant (OR 1.5, 95% CI 1.1–2.0, p = 0.01) and a higher frequency of breast cancer in first-degree relatives (OR 1.4, 95% CI 1.1–1.8, p = 0.01)." (PMID 36497357, 2022). "However, comprehensive genomic analysis revealed that activating mutations of certain Wnt/β-Catenin pathway components such as APC and β-Catenin were rarely observed in breast cancer, indicating that alternative mechanisms, probably Wnt-independent ways, exist to activate β-Catenin." (PMID 33407765, 2021). "Additionally, 70% of breast cancer tissues presented hypermethylation in the APC gene." (PMID 32850327, 2020). "In addition, inhibiting Src or JNK diminished the APC-mediated cell proliferation, suggesting that targeted inhibition of these signaling pathways downstream FAK appears as a promising strategy in APC-mutated breast cancers." (PMID 33266025, 2020). "To our knowledge, we are the first to show, using resources from a population-based follow-up study, that promoter methylation of APC, CCND2, HIN1, and TWIST1 may modify the inverse association between prediagnostic RPA and all-cause mortality following a breast cancer diagnosis." (PMID 28222775, 2017).
breast cancer (continued). "Therefore, we inferred that APC promoter methylation might be contribute to the corresponding biology and clinical outcome of breast cancer." (PMID 27191268, 2016). "Similarly, in cultured cells only one out of 24 screened human breast cancer cell lines (DU4475) had a truncating mutation in APC and none in β-catenin." (PMID 24887235, 2014). "Therefore, we next explored whether APC/β-catenin complexes at protrusion ends were found in breast cancer cells." (PMID 23302090, 2013). "To achieve a gene panel for developing a breast cancer blood-based test we quantitatively assessed the DNA methylation proportion of 248 CpG sites per sample (total of 31,248 sites in all analyzed samples) on 10 candidate genes (APC, BIN1, BMP6, BRCA1, CST6, ESR-b, GSTP1, P16, P21 and TIMP3)." (PMID 21283676, 2011). "We also show that certain Apc mutations are selected to achieve a specific level of β-catenin signaling optimal for mammary tumor development and explain partially the reason why breast cancers do not develop as frequently as colorectal tumors in patients that carry germline mutations in APC." (PMID 19197353, 2009). "To further explore the role of the APC/β-catenin pathway in breast carcinogenesis, we investigated the status of APC gene promoter methylation in primary breast cancers and in their non-cancerous breast tissue counterparts, as well as mutations of the APC and β- catenin genes." (PMID 11437404, 2001). "For instance, a recent systematic review identified several promising methylation biomarkers, including APC, RASSFI, and FOXA1, which show strong potential for early breast cancer detection in non-invasive assays." (PMID 39456897, 2024). "This combination treatment of CRISPR-mediated APC knockout MDA-MB-231 cells resulted in alterations in apoptosis, suggesting that Bcl-2 inhibition restores PTX sensitivity in APC knockout breast cancer cells." (PMID 38928449, 2024). "Using a panel of breast cancer cell lines, we measured the protein levels of APC, MDR1, and MRP1 to assess the correlation between APC and these transporters." (PMID 37108784, 2023). "Family history of breast cancer was observed either in first-, second- or third-degree relatives in all patients except in the patients carrying a VUS in the APC, BRIP1 and NF2 genes." (PMID 37277882, 2023). "One previous study found that breast cancer cells harbor higher RAD17 levels and a slower rate of Cdh1/APC-mediated RAD17 protein turnover compared with breast epithelial cells." (PMID 35844787, 2022). "For example, several attempts have been made to use genes that are commonly hypermethylated in breast tumors (GSTP1, RASSF1A, RARβ, APC, and DAPK) to generate a blood-based breast cancer methylation signature." (PMID 29614786, 2018). "For instance, an eight gene promoter hypermethylation panel (APC, BRCA1, BIN1, CST6, GSTP1, P16, P21, and TIMP3) had a reported sensitivity of 90% for identifying breast cancer patients." (PMID 29614786, 2018). "To address the relevance of APC and APC2 in human breast cancer, we interrogated primary invasive ductal carcinomas from the publically available METABRIC54 and TCGA BRCA55 cohorts." (PMID 27694902, 2017). "Taken together, our results represent a novel mechanism of GSK-3β, APC, and ICAT downregulation in breast cancer and a functionally and clinically relevant epigenetic mechanism of breast cancer pathogenesis." (PMID 26992223, 2016). "MiR-1229 upregulation drastically promoted breast cancer cell proliferation by inhibiting the expression of three key negative regulators (GSK-3β, APC, and ICAT) of the Wnt/β-catenin signaling pathway." (PMID 26992223, 2016). "Consistent with the tumor-suppressive effects of GSK-3β, APC, and ICAT, miR-1229 was upregulated in breast cancer, and its overexpression dramatically promoted breast cancer cell proliferation both in vitro and in vivo." (PMID 26992223, 2016).
breast cancer (continued). "MiR-1229 upregulation promoted cell proliferation in breast cancer both in vitro and in vivo, and activated Wnt/β-catenin signaling by directly targeting GSK-3β, APC, and inhibitor of β-catenin and T cell factor (ICAT)." (PMID 26992223, 2016). "In the human metaplastic breast cancer cell line MDA-MB-157, APC knockdown led to paclitaxel and cisplatin resistance." (PMID 26049416, 2015). "However, in breast cancer, where mutations in APC or β-catenin are not commonly reported, BCL9 overexpression may be a molecular mechanism contributing to aberrant Wnt activation and progression." (PMID 26384318, 2015). "Consistent with these notions, NOP14 increased APC and β-catenin levels, as well as GSK-3β phosphorylation level in breast cancer cells; furthermore, NOP14 inhibited the entry of β-catenin into the nucleus of breast cancer cells." (PMID 26213846, 2015). "For breast cancer, methylation has been noted in genes including BRCA1, p16, E-cadherin, H-cadherin, ATM, CST6, cyclin D2, PTEN, RASSF1A, APC, RARb2, GSTP1, ER, PR, as well as numerous other genes related to multiple pathways relevant for carcinogenesis." (PMID 24368439, 2014). "In the current study, we have characterized APC/β-catenin complexes at membrane protrusions in epithelial cells undergoing an epithelial-to-mesenchymal transition (EMT) and in human and mouse breast cancer cells." (PMID 23302090, 2013). "The five most frequently methylated TSGs (RASSF1, APC, CDH13, GSTP1, and CDKN2B) were the same in all groups of breast cancer and, with the exception of CDKN2B, were involved in other tumors from LS patients, too, although with variable frequencies." (PMID 22691310, 2012). "In the serum samples, promoter hypermethylation of some studied genes was correlated with clinical parameters (APC with histological grade G2; TIMP3 with late stage of breast cancer; BMP6, CST6, and TIMP3 with lymph node involvement)." (PMID 21283676, 2011). "Using hierarchical clustering in the plasma samples cohort, we found significant promoter hypermethylation of eight genes (APC, BIN1, BRCA1, CST6, GSTP1, P16, P21 and TIMP3) in patients' plasma of breast cancer patients compared with plasma of normal subjects." (PMID 21283676, 2011). "Accordingly, we detected high levels of CGI methylation for APC, HIC1 and RASSF1 in the breast carcinoma cell line MCF-7_wt and for APC and HIC1 in the doxorubicin sensitive cell line OVCAR-5." (PMID 20544021, 2010). "Of all two-marker combinations, the combination of APC and/or RASSF1A methylation was most frequently observed, in 47% of breast cancer cases." (PMID 19367284, 2009). "We selected a panel of three genes, namely, APC, RASSF1A and ESR1, for the detection of tumour-specific methylated DNA in serum samples from healthy controls (n=19) and breast cancer patients (n=79)." (PMID 19367284, 2009). "RASSF1A had the highest frequency of hypermethylation with 35% of breast cancer cases being positive, followed by APC and ESR1 being methylated in 29 and 20% of breast cancer cases, respectively." (PMID 19367284, 2009). "We selected three genes, namely, APC, RASSF1A and ESR1, which are known to be frequently hypermethylated in breast cancer." (PMID 19367284, 2009). "Furthermore, the combination of anti-PD1 antibodies with PEG-TAT-APC11 or NP-APC11 demonstrated synergistic anti-tumor effects in APC-mutant CRC, which is typically resistant to anti-PD1 therapy, as well as in melanoma and breast cancer models." (PMID 41486293, 2026). "Additionally, a total of 16 gene records were retrieved for breast cancer, which includes but is not limited to BRCA1, RB1, APC and PTEN." (PMID 37195695, 2023).